CRISPLD1 (cysteine rich secretory protein LCCL domain containing 1)
Synonyms: CRISP-10; CRISP10; LCRISP1; Cocoacrisp; DKFZp762F133; CAPLD1
Tractability: Antibody: UniProt places it where antibodies can reach, with high confidence; UniProt predicts a signal peptide or a membrane-spanning region; its Gene Ontology location is reachable by antibodies, with medium confidence.
Gene: Protein-coding gene on chromosome 8 (74,984,502 to 75,034,558, forward strand). Ensembl gene ENSG00000121005.
Subcellular location: Secreted
Gene Ontology:
Biological process: face morphogenesis
Cellular component: extracellular exosome; extracellular region
Genetic constraint (gnomAD): Loss-of-function variants: 40 observed, 49.66 expected, observed/expected ratio (o/e) 0.81, 90% interval 0.62 to 1.05. The upper end of that interval is the gene's LOEUF score, 1.05, which puts it in group 4 of 6, group 1 being the genes least tolerant of losing a copy. Missense variants: 480 observed, 497.95 expected, observed/expected ratio (o/e) 0.96, 90% interval 0.89 to 1.04. Synonymous variants: 153 observed, 167.3 expected, observed/expected ratio (o/e) 0.91, 90% interval 0.8 to 1.05.
Homologues: Orthologues: chimpanzee CRISPLD1 (99% identical), macaque CRISPLD1 (98% identical), dog CRISPLD1 (97% identical), pig CRISPLD1 (97% identical), rabbit CRISPLD1 (97% identical), guinea pig CRISPLD1 (96% identical), mouse Crispld1 (95% identical), rat Crispld1 (84% identical), tropical clawed frog pi15 (66% identical), Drosophila melanogaster CG42564 (15% identical), Caenorhabditis elegans scl-10 (12% identical), Drosophila melanogaster CG34002 (12% identical), and 41 more. Paralogues in human: CRISPLD2 (57% identical), PI15 (26% identical), R3HDML (23% identical), CLEC18A (19% identical), CLEC18B (19% identical), CLEC18C (19% identical), GLIPR1 (17% identical), CRISP3 (16% identical), CRISP2 (15% identical), CRISP1 (15% identical), GLIPR1L2 (14% identical), GLIPR1L1 (13% identical), and 1 more.
Diseases named in the same sentence as CRISPLD1 in open-access papers:
CRISPLD1 is named in the same sentence as 14 diseases in open-access papers, as found by Europe PMC text mining. Sharing a sentence is not in itself a finding about the gene and the disease. The quoted sentences say what the papers report.
coronary artery disease (1 paper, 2020). "Only recently, it has been shown that CRISPLD1 polymorphisms alter antiplatelet potency of clopidogrel in coronary artery disease patients in Chinese Han and that CRISPLD1 is differentially methylated during male infertility." (PMID 32146539, 2020).
deafness (1 paper, 2018). An inherited or acquired condition characterized by the complete loss of the ability to hear from one or both ears. "Multiple ECM genes are also upregulated in the upper-bulge compartment, including Aspn, Crispld1, Egfl6, and the deafness-related ECM genes Col4a3 and Col4a4." (PMID 30355452, 2018).
endometrioid tumor (1 paper, 2019). A benign, borderline, or malignant epithelial tumor of the female reproductive system characterized by the presence of glands and/or cysts lined by neoplastic cells that resemble endometrial cells. "ANO1, SOX17, CGNL1, DACH1, RUNDC3B, SH3YL1 and CRISPLD1 were significantly downregulated both in papillary serous tumors and endometrioid tumor." (PMID 30813939, 2019).
pulmonary fibrosis (1 paper, 2020). Chronic progressive interstitial lung disorder characterized by the replacement of the lung tissue by connective tissue, leading to progressive dyspnea, respiratory failure, or right heart failure. "CRISPLD1 was described to be expressed in lung fibroblasts and was discussed as a novel biomarker for experimental pulmonary fibrosis." (PMID 32146539, 2020).
CRISPLD1 also shares sentences with these, for which no sentence is quoted: cancer (2 papers); breast carcinoma (1); colorectal cancer (1); endometrial cancer (1); heart failure (1); lung carcinoma (1); male infertility (1); oral cancer (1); ovarian carcinoma (1); renal cell carcinoma (1).